UBQLN4 (ubiquilin 4)
Description:
Regulator of protein degradation that mediates the proteasomal targeting of misfolded, mislocalized or accumulated proteins. Acts by binding polyubiquitin chains of target proteins via its UBA domain and by interacting with subunits of the proteasome via its ubiquitin-like domain. Key regulator of DNA repair that represses homologous recombination repair: in response to DNA damage, recruited to sites of DNA damage following phosphorylation by ATM and acts by binding and removing ubiquitinated MRE11 from damaged chromatin, leading to MRE11 degradation by the proteasome. MRE11 degradation prevents homologous recombination repair, redirecting double-strand break repair toward non-homologous end joining (NHEJ). Specifically recognizes and binds mislocalized transmembrane-containing proteins and targets them to proteasomal degradation. Collaborates with DESI1/POST in the export of ubiquitinated proteins from the nucleus to the cytoplasm. Also plays a role in the regulation of the proteasomal degradation of non-ubiquitinated GJA1 (By similarity). Acts as an adapter protein that recruits UBQLN1 to the autophagy machinery. Mediates the association of UBQLN1 with autophagosomes and the autophagy-related protein LC3 (MAP1LC3A/B/C) and may assist in the maturation of autophagosomes to autolysosomes by mediating autophagosome-lysosome fusion.
Synonyms: A1Up; CIP75; C1orf6; UBIN; A1U
Tractability: PROTAC: UniProt records ubiquitination sites on it; ubiquitination databases record sites on it; its protein half-life has been measured.
Gene: Protein-coding gene on chromosome 1 (156,035,299 to 156,053,798, reverse strand). Ensembl gene ENSG00000160803.
Subcellular location: Nucleus; Cytoplasm; Chromosome; Endoplasmic reticulum; Cytoplasm, perinuclear region; Cytoplasmic vesicle, autophagosome
Subcellular location (Human Protein Atlas): Nucleoplasm
Gene Ontology:
Molecular function: identical protein binding; K48-linked polyubiquitin modification-dependent protein binding; polyubiquitin modification-dependent protein binding; protein binding
Biological process: DNA damage response; negative regulation of autophagosome maturation; negative regulation of double-strand break repair via homologous recombination; regulation of proteasomal ubiquitin-dependent protein catabolic process; ubiquitin-dependent protein catabolic process; cellular response to stress; regulation of cellular response to stress; regulation of proteasomal protein catabolic process
Cellular component: autophagosome; chromosome; cytoplasm; cytosol; cytosolic proteasome complex; nuclear proteasome complex; nucleoplasm; nucleus; protein-containing complex; site of DNA damage; endoplasmic reticulum; endoplasmic reticulum membrane; perinuclear region of cytoplasm
Genetic constraint (gnomAD): Loss-of-function variants: 10 observed, 54.06 expected, observed/expected ratio (o/e) 0.18, 90% interval 0.11 to 0.31. The upper end of that interval is the gene's LOEUF score, 0.31, which puts it in group 1 of 6, group 1 being the genes least tolerant of losing a copy. Missense variants: 408 observed, 734.71 expected, observed/expected ratio (o/e) 0.56, 90% interval 0.51 to 0.6. Synonymous variants: 255 observed, 293.59 expected, observed/expected ratio (o/e) 0.87, 90% interval 0.78 to 0.96.
Homologues: Orthologues: chimpanzee UBQLN4 (99% identical), macaque UBQLN4 (99% identical), pig UBQLN4 (98% identical), dog UBQLN4 (97% identical), guinea pig UBQLN4 (96% identical), rabbit UBQLN4 (93% identical), mouse Ubqln4 (92% identical), rat Ubqln4 (92% identical), tropical clawed frog ubqln4 (75% identical), zebrafish ubqln4 (71% identical), Drosophila melanogaster CG31528 (16% identical). Paralogues in human: UBQLN1 (62% identical), UBQLN2 (58% identical), UBQLN3 (40% identical), UBQLNL (24% identical), UBL7 (16% identical).
Diseases named in the same sentence as UBQLN4 in open-access papers:
UBQLN4 is named in the same sentence as 57 diseases in open-access papers, as found by Europe PMC text mining. Sharing a sentence is not in itself a finding about the gene and the disease. The quoted sentences say what the papers report.
hepatocellular carcinoma (5 papers, 2020 to 2024). A malignant tumor that arises from hepatocytes. "In hepatocellular carcinoma, UBQLN4 promoted tumor proliferation and invasion by regulating wnt- β-catenin pathway, while miR-370 could downregulate UBQLN4 to inhibit tumor progression." (PMID 34539785, 2021). "Indeed, Yu and co-workers showed that miR-370/UBQLN4 axis regulates the formation and progression of hepatocellular carcinoma." (PMID 32549375, 2020). "A previous study in hepatocellular carcinoma (HCC) showed that miR-370 decreases UBQLN4 mRNA/protein levels." (PMID 36291176, 2022). "However, the underlying mechanism of UBQLN4 in the development of hepatocellular carcinoma (HCC) has not been elucidated." (PMID 31911755, 2020).
gastric cancer (4 papers, 2019 to 2024). A primary or metastatic malignant neoplasm involving the stomach. "Here, we reported that Ubqln4 was downregulated in gastric cancer tissues and functioned as a tumor suppressor by inhibiting gastric cancer cell proliferation in vivo and in vitro." (PMID 29899380, 2019). "Our findings not only establish the anti-tumor potential of Ubqln4 in gastric cancer but also reveal a role for Ubqln4 in regulation of the cell cycle and cellular senescence via stabilizing p21." (PMID 29899380, 2019).
melanoma (4 papers, 2021 to 2022). A malignant, usually aggressive tumor composed of atypical, neoplastic melanocytes. "By inhibiting UBQLN4 and promoting ubiquitination in melanoma cells, Albendazole has an anti-tumor immunological impact, culminating in PD-L1 protein degradation." (PMID 35907881, 2022). "Bioinformatics and anti-PD-1 therapy melanoma patients samples analysis were used to assess the level of UBQLN4/PD-L1 in the therapeutic efficacy of anti-PD-1 therapy." (PMID 35577504, 2022). "Previous studies have reported that UBQLN4 was overexpressed in neuroblastoma, melanoma, and HCC, related to poor OS." (PMID 34539785, 2021). "Significantly, UBQLN4 and PD-L1 levels were higher in the tumor region of responders versus non-responders and correlated with better progression-free survival and overall survival in anti-PD-1 therapy melanoma patients." (PMID 35577504, 2022). "It was reported that the increase of UBQLN4 in neuroblastoma and melanoma decreased survival." (PMID 34539785, 2021). "Ubiquilin 4 (UBQLN4) suppresses PD-L1 ubiquitination and promotes protein stability in melanoma." (PMID 35907881, 2022).
amyotrophic lateral sclerosis (3 papers, 2019 to 2024). Amyotrophic lateral sclerosis (ALS) is a neurodegenerative disease characterized by progressive muscular paralysis reflecting degeneration of motor neurons in the primary motor cortex, corticospinal tracts, brainstem and spinal cord. "UBQLN4 is associated with various cellular processes, including apoptosis, amyotrophic lateral sclerosis, immune-related therapies and DNA damage repair." (PMID 38969831, 2024). "But recently, a researcher found that a novel variant in UBQLN4 is associated with amyotrophic lateral sclerosis (ALS) and show that its expression compromises motor axon morphogenesis in mouse motor neurons and in zebrafish." (PMID 31888623, 2019). "Proteins related to neurodegenerative disease were also found to be significantly changed in abundance, including proteins involved in Parkinson’s disease (PARK7) and amyotrophic lateral sclerosis (ubiquilin-4, superoxide dismutase, and RNA-binding protein FUS)." (PMID 34073856, 2021).
esophageal squamous cell carcinoma (3 papers, 2021). Esophageal squamous cell carcinoma (ESCC) is a type of esophageal carcinoma (EC) that can affect any part of the esophagus, but is usually located in the upper or middle third. "Moreover, UBQLN4 binds to MRE11 and promotes MRE11 degradation, leading to cisplatin-resistance in cancer cells, i.e., esophageal squamous cell carcinoma (ESCC)." (PMID 34440334, 2021).
mesothelioma (3 papers, 2021 to 2022). A usually malignant and aggressive neoplasm of the mesothelium which is often associated with exposure to asbestos. "Collectively, these data suggested that UBQLN4 upregulation may be associated with development or prognosis of mesotheliomas." (PMID 34245648, 2021). "Taken together, we uncover that about fifty potential substrates for ATM and clarify the mechanism that UBQLN4 inhibits the apoptosis in mesothelioma by phosphorylating the site of Ser318 and stabilizing BCL2A1 and BCL2L10." (PMID 34245648, 2021). "The colony formation and cell viability assays of human mesothelioma NCI‐H2452 cells indicated that UBQLN4‐silencing inhibited mesothelioma cell colony formation and significantly enhanced the mesothelioma cell sensitivity to DNA damaging drugs." (PMID 34245648, 2021). "Stronger UBQLN4 staining was observed in the mesothelioma tissues compared with that of adjacent tissues." (PMID 34245648, 2021). "Phosphorylated UBQLN4 prevented cytochrome c release and inhibited apoptosis in mesothelioma during DNA damage by stabilizing BCL2A1 and BCL2L10." (PMID 34245648, 2021). "Mechanically, UBQLN4 regulates mesothelioma cell apoptosis in response to DNA damage by phosphorylating the site of Ser318." (PMID 34245648, 2021). "Our results thus not only revealed lots of potential candidates for ATM but also unveiled a mechanism that a new ATM substrate UBQLN4 regulates apoptosis in mesothelioma by stabilizing BCL2A1 and BCL2L10." (PMID 34245648, 2021). "The finding that UBQLN4 is high expressed in mesothelioma and knockdown of UBQLN4 enhances the sensitivity to DNA damage drugs may provide a new molecular strategy for the treatment of malignant mesothelioma." (PMID 34245648, 2021). "Taken together, our data suggest that ATM‐mediated phosphorylation of UBQLN4 at Ser318 may regulate mesothelioma cell apoptosis in response to DNA damage." (PMID 34245648, 2021). "UBQLN4 may be of great therapeutic potential for targeting mesothelioma and other diseases." (PMID 34245648, 2021). "Furthermore, UBQLN4 inhibits the apoptosis in mesothelioma by stabilizing BCL2A1 and BCL2L10." (PMID 34245648, 2021). "In addition to the elevated gene expression, immunohistochemistry (IHC) analysis of human mesothelioma tissue arrays containing 30 mesothelioma tissues and 10 adjacent normal tissues showed that UBQLN4 expression was also significantly increased at the protein level." (PMID 34245648, 2021). "Therefore, we further investigated the anti‐apoptotic mechanisms of BCL2A1 and BCL2L10 in mesothelioma and found that UBQLN4 could prevent MOMP in mesothelioma cells with CPT treatment." (PMID 34245648, 2021). "All three proteins, UBQLN4, BCL2A1, and BCL2L10, were highly expressed in all cases of mesothelioma tissues." (PMID 34245648, 2021). "Our further study demonstrated that UBQLN4 acts as an anti‐apoptotic factor, which interacts with and stabilizes the anti‐apoptotic proteins BCL2A1 and BCL2L10, and regulates mesothelioma cell apoptosis in response to DNA damage." (PMID 34245648, 2021). "In this study, we not only identified UBQLN4 as a substrate for ATM, but also found that UBQLN4 interacts with and stabilizes the anti‐apoptotic proteins Bcl‐2‐related protein A1 (BCL2A1) and Bcl‐2‐like protein 10 (BCL2L10) and prevents mesothelioma cell apoptosis in response to DNA damage." (PMID 34245648, 2021). "We found UBQLN4 as a new ATM substrate, which was upregulated in mesothelioma." (PMID 34245648, 2021).
colorectal cancer (2 papers, 2021 to 2024). A primary or metastatic malignant neoplasm that affects the colon or rectum. "Nevertheless, the biological function and detailed mechanisms of UBQLN4 in colorectal cancer (CRC) development and progression remain unclear." (PMID 34930912, 2021).
esophageal cancer (2 papers, 2022). A primary or metastatic malignant neoplasm involving the esophagus. "UBQLN4 is upregulated at both mRNA and protein levels and the most significant values were observed in liver, breast, ovarian, lung, and esophageal cancers." (PMID 36291176, 2022). "We observed that UBQLN4 and PD-L1 were upregulated in most cancer types, including esophageal carcinoma, head and neck squamous cell carcinoma, adenocarcinoma of the stomach and lung adenocarcinoma." (PMID 35577504, 2022).
glioma (2 papers, 2021 to 2022). A benign or malignant brain and spinal cord tumor that arises from glial cells (astrocytes, oligodendrocytes, ependymal cells). "In the current study, we found that as the grade of glioma increased, the expression of UBQLN4 gradually decreased, and its high expression was associated with shorter survival time of patients." (PMID 35571034, 2022).
lung adenocarcinoma (2 papers, 2022 to 2023). A carcinoma that arises from the lung and is characterized by the presence of malignant glandular epithelial cells. "Interestingly, we observed an increase in the expression of oncogene MYC following the loss of UBQLN1 or UBQLN2, but not with UBQLN3 or UBQLN4 in lung adenocarcinoma cells." (PMID 37444499, 2023).
lung carcinoma (2 papers, 2021 to 2024). "For further verification, we evaluated the expression level of UBQLN4 in 80 NSCLC patients’ tissues and adjacent normal tissues using IHC, and the results showed that UBQLN4 was low in normal lung tissues but high in lung cancer tissues, p< 0.05." (PMID 38969831, 2024).
motor neuron disease (2 papers, 2017 to 2022). "Further supporting a link between 2,4-DAB and motor neuron disease, the ALS-associated gene Ubiquilin 4 (UBQLN4) was among the top ten most strongly downregulated proteins in our 2,4-DAB-exposed samples." (PMID 35029765, 2022). "It is notable that our findings link UBQLN4 with beta-catenin in the context of ALS, as recent work suggested a similar role for beta-catenin signaling in the pediatric motor neuron disease Spinal Muscular Atrophy (SMA)." (PMID 28463112, 2017).
ovarian carcinoma (2 papers, 2022). A malignant neoplasm originating from the surface ovarian epithelium. "Our findings suggest that UBQLN4 mRNA levels allowed for triaging ovarian cancer patients that will receive platinum drugs or PARPi therapies." (PMID 36291176, 2022). "In ovarian cancer cell lines, UBQLN4 mRNA levels positively correlated with cisplatin AUC values (Pearson correlation coefficient = 0.58, p = 0.0050)." (PMID 36291176, 2022). "In ovarian cancer cell lines, UBQLN4 mRNA levels negatively correlated with Olaparib AUC values (Pearson correlation coefficient = −0.31, p = 0.18)." (PMID 36291176, 2022). "Ovarian cancer cell lines with high UBQLN4 mRNA levels had the lowest sensitivity to cisplatin treatment (Mann–Whitney U test: p = 0.0041)." (PMID 36291176, 2022). "Ovarian cancer cell lines with high UBQLN4 mRNA levels were platinum-based chemotherapy resistant, while they were more sensitive to poly (adenosine diphosphate-ribose) polymerase inhibitors (PARPi)." (PMID 36291176, 2022). "Interestingly, ovarian cancer cell lines which have high mRNA levels of UBQLN4 showed cisplatin resistance and Olaparib sensitivity at the same time." (PMID 36291176, 2022). "We found that the expression of six genes (BCLAF1, FBLN1, ARHGAP23, STON2, UBQLN4, and ATP2B1) had a significant positive correlation with the survival rate of patients with ovarian cancer." (PMID 35978436, 2022). "In this study, we also showed that parent genes such as BCLAF1, FBLN1, ARHGAP23, STON2, UBQLN4, and ATP2B1 were significantly positively correlated with the survival rate of patients with ovarian cancer." (PMID 35978436, 2022). "Interestingly, the ovarian cancer cell line OVK18, which showed the highest UBQLN4 mRNA levels in CCLE had the highest sensitivity to Olaparib, despite having the lowest sensitivity to cisplatin treatment." (PMID 36291176, 2022).
Cerebellar atrophy (1 paper, 2016). Cerebellar atrophy is defined as a cerebellum with initially normal structures, in a posterior fossa with normal size, which displays enlarged fissures (interfolial spaces) in comparison to the foliae secondary to loss of tissue. "It is not yet associated with human disease, however the de novo variant of ubiquilin-4 might have a role in the cerebellar atrophy of this patient." (PMID 26990090, 2016).
Cirrhosis (1 paper, 2020). A chronic disorder of the liver in which liver tissue becomes scarred and is partially replaced by regenerative nodules and fibrotic tissue resulting in loss of liver function. "Besides, UBQLN4 expression was higher in HCC tissues than in cirrhosis liver, low-grade dysplastic liver and high-grade dysplastic liver tissues." (PMID 31911755, 2020).
esophageal adenocarcinoma (1 paper, 2022). A malignant tumor with glandular differentiation arising predominantly from Barrett mucosa in the lower third of the esophagus. "Interestingly, UBQLN4 mRNA levels did not change across different histopathology subtypes, such as 1) among the different subtypes of BRCA, and 2) between adenocarcinoma and mucinous carcinoma in COAD/READ and, 3) between esophageal adenocarcinoma (ESAD) and ESCC." (PMID 36291176, 2022).
gastric tumor (1 paper, 2019). "Together these data indicated that Ubqln4 functions as a tumor-inhibiting factor and negatively regulates gastric tumor growth." (PMID 29899380, 2019).
lymph node metastasis (1 paper, 2021). "High expression of UBQLN4 is positively associated with the CRC size, TNM stage and lymph node metastasis (N stage), and patients with high UBQLN4 expression have a poor prognosis." (PMID 34930912, 2021). "High UBQLN4 expression was positively correlated with the tumor size (p = 0.017), TNM stage (p = 0.038), and lymph node metastasis (N stage) (p = 0.020)." (PMID 34930912, 2021).
neuroblastoma (1 paper, 2021). Neuroblastoma (NB) is the most common solid, extracranial childhood tumor. "It was reported that overexpression of UBQLN4 in neuroblastoma cells increased the sensitivity of PARP inhibitors." (PMID 34539785, 2021).
non-small cell lung carcinoma (1 paper, 2024). A group of at least three distinct histological types of lung cancer, including non-small cell squamous cell carcinoma, adenocarcinoma, and large cell carcinoma. "Here, we investigated for the first time the functional role and mechanism of UBQLN4 in non-small cell lung cancer (NSCLC)." (PMID 38969831, 2024).
renal carcinoma (1 paper, 2020). A carcinoma arising from the epithelium of the renal parenchyma or the renal pelvis. "Ubiquilin-4 was overexpressed in most solid tumor tissues except in renal carcinoma." (PMID 31911755, 2020).
spinocerebellar ataxia type 1 (1 paper, 2007). Spinocerebellar ataxia type 1 (SCA1) is a subtype of type I autosomal dominant cerebellar ataxia (ADCA type I) characterized by dysarthria, writing difficulties, limb ataxia, and commonly nystagmus and saccadic abnormalities. "Ubiquilin-4 is linked to spinocerebellar ataxia type 1 (SCA1), an inherited neurodegenerative disease, which primarily affects the brainstem, spinocerebellar tracts and cerebellar Purkinje cells." (PMID 18047733, 2007).
triple-negative breast carcinoma (1 paper, 2022). An invasive breast carcinoma which is negative for expression of estrogen receptor (ER), progesterone receptor (PR), and human epidermal growth factor receptor 2 (HER2). "We have shown that elevation of UBQLN4 relates to triple-negative breast cancer (TNBC) and neuroblastoma outcomes." (PMID 36291176, 2022). "Furthermore, our recent study has shown that UBQLN4 targets STING in triple-negative breast cancer." (PMID 36291176, 2022).